NPRL3 (NPR3 like, GATOR1 complex subunit)
Diseases named in the same sentence as NPRL3 in open-access papers (continued):
Sharing a sentence is not in itself a finding about the gene and the disease.
iron deficiency (1 paper, 2025). "Interestingly, NPRL3-KO erythroblasts failed to appropriately regulate pS6 in response to iron deficiency and EPO deprivation (separately, in replete amino acid conditions)." (PMID 40128524, 2025).
lung carcinoma (1 paper, 2025). "We found that not only NPLR2, but also NPRL3 and DEPDC5 are downregulated in these types of lung cancer." (PMID 41469472, 2025).
cancer (8 papers, 2015 to 2025). A tumor composed of atypical neoplastic, often pleomorphic cells that invade other tissues. "There are fewer articles describing the role of NPRL3 and DEPDC5 in cancers, probably because NPRL2 has a higher cancer-associated mutation frequency among GATOR1 components." (PMID 41469472, 2025). "For example, GOLGA7, ITPK1, and NPRL3 were correlated with increased drug resistance of cancer cells to Dasatinib, Zoledronate, PF-06463922, Brigatinib, LDK-378, Vinorelbine, Carfilzomib, and Bortezomib, respectively." (PMID 34970268, 2021). "The GATOR1 complex, which consists of DEPDC5, Nprl2 and Nprl3, has GAP activity for RagA/B, and its inactivating mutations in cancers result in mTORC1 hyperactivation." (PMID 29199950, 2017). "Second, we predict that cancers with activating mutations in RHEB, or inactivating mutations in DEPDC5, NPRL2, and NPRL3, will show similar strong response to rapalogs." (PMID 26137524, 2015). "Surprisingly, during the last decade, not a single article reported a study about the involvement of NPRL3 in cancer and drug resistance, even if in the COSMIC database there are almost three times more somatic cancer mutations listed for NPRL3 than for its paralogue NPRL2." (PMID 34685669, 2021). "The selection of NPRL3, a component of the GATOR1 complex involved in mTOR signaling regulation, aligns with known dysregulation of growth signaling pathways in cancer." (PMID 40227838, 2025). "NPRL2, along with NPRL3 and DEPDC5, forms the GATOR1 complex, an upstream regulator of the mTORС1, the function of which is perturbed in many cancers, particularly those resistant to cisplatin." (PMID 41469472, 2025). "Even though NPRL3 is a paralogue of NPRL2, its alternations in cancer are less recurrent." (PMID 34685669, 2021).
tumor (3 papers, 2022 to 2025). "Specifically, we focused on the role of key lncRNAs, miRNAs, and mRNAs in LUADBM progression, with a particular emphasis on the XLOC_006941/hsa-miR-543/NPRL3 axis, and the involvement of GATA3 and Th2 cells in shaping the tumor microenvironment." (PMID 39941924, 2025).
infection (1 paper, 2024). The state of being infected such as from the introduction of a foreign agent such as serum, vaccine, antigenic substance or organism. "Therefore, this restricted milieu may amplify Ser/5-HT-promoted astrocyte infection by T. cruzi, which might be favored by the inability of mouse and human cortical astrocytes (GFAP+ cells) to express the inflammasome NPRL3." (PMID 38776344, 2024).
neurodegenerative disease (1 paper, 2023). A disorder of the central nervous system characterized by gradual and progressive loss of neural tissue and neurologic function. "It was shown that enhanced autophagy was associated with extended lifespan in model organisms (such as worm and mouse), and increasing evidences indicated that several genes (including LAMTOR4, LAMTOR2 and NPRL3) involved in mTOR network regulated autophagy and neurodegenerative diseases." (PMID 37582720, 2023).
NPRL3 also shares sentences with these, for which no sentence is quoted: cortical dysplasia (3 papers); infantile spasms (2); 22q11.2 deletion syndrome (1); anaemia (1); Central apnea (1); cerebrovascular disease (1); developmental and epileptic encephalopathies (1); familial focal epilepsy with variable foci (1); generalized epilepsy (1); genetic disorders (1); glioblastoma (1); hemimegalencephaly (1); hyperlipidemia (1); Hypertension (1); hypothalamic hamartoma (1); Lissencephaly (1); malaria (1); myocardial infarction (1); neurological disorders (1); Parkinson disease (1); peripheral neuropathy (1); sclerosis tuberous (1).